RAC1 (Rac family small GTPase 1)
Diseases named in the same sentence as RAC1 in open-access papers (continued):
Sharing a sentence is not in itself a finding about the gene and the disease.
bladder cancer (continued). "This is the case, for example, for the microRNA miR-142-3p, which interacts directly with Rac1 in bladder cancer cells to inhibit their proliferation but also their migration and invasion." (PMID 35740379, 2022). "Other factors are implicated in Rac1-mediated EMT, such as the metabolic enzyme AKR1C1 (aldo-keto reductase 1C1), which mediates the invasive potential and drug resistance of metastatic bladder cancer cells." (PMID 35740379, 2022). "Secondly, we found that the stemness and the invasiveness of bladder cancer cells induced by SNHG1 over-expression are closely linked and are both driven by the over-expression of Rac1." (PMID 36077697, 2022). "The contribution of the Rac1 protein to tumorigenesis, tumor progression, epithelial-mesenchymal transition of bladder cancer cells and their metastasis has been analyzed." (PMID 35740379, 2022). "The inhibition of AKR1C1 reduces the invasion/metastatic potential of bladder cancer cells via the regulation of the Rac1/Src/Akt pathway and modulation of the production of inflammatory cytokines, such as interleukin 1β (IL-1β)." (PMID 35740379, 2022). "Having demonstrated the effects of the SNHG1/DNMT3A/miR-129-2-5p/Rac1 effector pathway on promoting bladder cancer cell stemness and invasion, we investigated more directly the functional relationship between stemness and invasion." (PMID 36077697, 2022). "It is therefore possible to slow down the proliferation and migration of bladder cancer cells via a brake on Rac1." (PMID 35740379, 2022). "Our search of the Human Protein Atlas database for muscle-invasive bladder cancer showed that patients with high levels of Rac1 expression faired significantly worse than patients with low levels of Rac1 expression (p = 0.0087)." (PMID 36077697, 2022). "Rac1 activation by TIAM1 is an important component of the OPN-CD44-TIAM1-Rac1-mediated mechanism of invasion in bladder cancer cell lines." (PMID 33203146, 2020). "CSTF2 has previously been implicated as a promoter of lung and bladder cancer, through the regulation of ERBB2 and RAC1 3′ UTRs, respectively." (PMID 32029502, 2020). "We showed that laminin stimulates Lu/BCAM to increase the adhesion of NIH-Lu and bladder cancer cells through RhoA/Rac1 signalling pathway." (PMID 28841878, 2017). "The marked effects of rictor silencing on cell spreading, migration, and invasion are consistent with our biochemical results suggesting that Rac1 is major target of mTORC2 in bladder cancer." (PMID 24312263, 2013). "In our experiments with J82 bladder cancer cells, rictor gene-silencing substantially decreased Rac1 activation while having a more modest effect on RhoA." (PMID 24312263, 2013). "In conclusion, our studies demonstrate that mTORC2 is a critical regulator of bladder cancer migration and invasion, with effects mediated primarily through Rac1." (PMID 24312263, 2013). "One study showed that Rac1 regulates bladder cancer cell invasion and actin reorganization downstream of integrin-linked kinase (ILK)." (PMID 24312263, 2013). "In addition, isorhapontigenin inhibits human bladder cancer invasion via an upstream regulatory Dicer/miR-145/SOX2/miR-365a/RAC1 cascade resulting in MKK7/JNK activation and autophagy induction." (PMID 36766800, 2023). "By defining a functional signaling pathway, i.e., SNHG1/DNMT3A/miR-129-2-5p/Rac1, that drives stemness and invasion in advanced bladder cancer cells, our study should spur additional investigation into the value of therapeutically targeting components of this pathway." (PMID 36077697, 2022). "The enhanced expression of Rac1 is certainly not the sole key element contributing to bladder carcinogenesis; the modulation of the full Rho-GTPase axis has been implicated in bladder cancer tumorigenesis." (PMID 35740379, 2022).
bladder cancer (continued). "Our own study with a bladder cancer cell line (J82) showed that rictor gene silencing reduced Rac1-GTP levels to 60.2% of rictor-expressing cells, suggesting that Rac1 may be a major target of mTORC2 in bladder cancer." (PMID 35326708, 2022). "Overall, we believe that the identification of the SNHG1/DNMT3A/miR-129-2-5p/Rac1 effector pathway that plays a major role in driving bladder cancer stemness and invasion may help develop a new therapeutic approach to treat this difficult disease." (PMID 36077697, 2022). "The SHCBP1/RACGAP1/RAC1 interaction could therefore serve as a potential candidate for designing novel targeted therapeutic strategies for bladder cancer in clinical management." (PMID 35013128, 2022). "Via this relay, SHCBP1 can inactivate Rac1 and promote bladder cancer progression." (PMID 35740379, 2022). "The Rac1 axis is a regulatory mechanism of bladder cancer progression." (PMID 35740379, 2022). "It would be of considerable interest to next test the various Rac1 inhibitors, first in cell-based systems and then in animal models of bladder cancer, to sort out which specific inhibitors are effective in curtailing bladder cancer growth and progression." (PMID 36077697, 2022). "The Rac1 gene, like other Rho-related genes, is frequently overexpressed in urothelial cell carcinoma, and the altered expression of the corresponding proteins plays an important role in the genesis and progression of cancers of the urinary bladder." (PMID 35740379, 2022). "The involvement of Rac1 as a major downstream target of mTORC2 in the regulation of bladder cancer invasion may link a number of recent findings in the literature." (PMID 24312263, 2013). "Therefore, the upregulation of EP300, PTPN11, and RAC1 genes may play a role in the development of NDV persistent infection in EJ28 bladder cancer cell line." (PMID 37147328, 2023). "In bladder cancer, nuclear translocation of SHCBP1 induced by EGF inhibits RACGAP1-mediated RAC1 inactivation to promote cancer cell proliferation and invasiveness." (PMID 40799237, 2025). "Our data strongly suggest that the SNHG1/DNMT3A/miR-129-2-5p/Rac1 effector pathway drives stem-cell-like and invasive behaviors in MIBC, a deadly form of bladder cancer." (PMID 36077697, 2022). "Through Rac1, SNHG1 also markedly stimulates the stem-cell-like sphere formation of bladder cancer cells." (PMID 36077697, 2022). "Small molecules selectively targeting Rac1 have been discovered or designed, and two of them—NSC23766 and EHT 1864—have revealed activities against bladder cancer." (PMID 35740379, 2022). "In bladder cancer cells, the entry of the BCG was found to rely on the expression of Rac1 and its effector kinase Pak1 (as well as Cdc42) via a process of micropinocytosis." (PMID 35740379, 2022). "Our study showed that hAM homogenate strongly reduced the expression of Cdc42 and Rac1/2/3 in non-invasive and invasive bladder cancer urothelial cells, while hAM extract had no inhibitory effect." (PMID 37932474, 2023). "Rac1 plays roles in tumorigenesis, tumor progression, EMT and metastasis of bladder cancer cells." (PMID 35740379, 2022). "In this study, we found that cell movement is RAC1-dependent in bladder cancer, and RAC1 activity, but not RhoA and CDC42, is inhibited by RACGAP1, which is partially reversed following SHCBP1 ectopic expression." (PMID 35013128, 2022).
bladder cancer (continued). "By identifying the DNMT3A/miR-129-2-5p/Rac1 signaling pathway downstream of SNHG1 that is operative in advanced bladder cancer cells, we are in no way ruling out other potential pathways or components that might also mediate the activities of SNHG1." (PMID 36077697, 2022). "The role and targeting of Rac1 in cancers have been debated in recent years, but the specific implication of Rac1 in OAB and bladder cancer has not been assessed." (PMID 35740379, 2022).
liver cancer (24 papers, 2013 to 2025). An epithelial or non-epithelial malignant neoplasm that arises from the liver. "Both Rac1 and RhoA have been implicated in invasive behavior of various tumor types including breast, lung, colon, and liver cancer." (PMID 35241781, 2022). "Kaplan-Meier survival curves showed that higher expressions of CD147, ARNO, and Rac1 mRNA were significantly associated with shorter overall survival (OS), whereas Arf6 mRNA expression was slightly associated with the survival of liver cancer patients." (PMID 31752956, 2019). "Subsequently, NPM1 translocated from the nucleus to the cytoplasm and plasma, where it interacted with ELMO1, activated small GTPases (Rac1), and ultimately triggered actin polymerisation and liver cancer cell migration." (PMID 37251542, 2023). "More studies have found that abnormal expression of Rac1 in thyroid cancer and liver cancer can regulate the malignant behavior of tumors." (PMID 35682879, 2022). "Meanwhile, some mechanisms of the function of Rac1 in drug resistance and liver cancer were discussed." (PMID 35847360, 2022). "To identify pharmacological means to alter 2D cell migration in liver cancer, we targeted key regulators of the Rho GTPases, including calcium signaling, Rac1, PAK4, LIMK1, MLCK, and actomyosin contractility." (PMID 35241781, 2022). "As a result, elucidating the features of the immune pattern triggered by RAC1 is critical for liver cancer immunotherapy and prognosis prediction." (PMID 35493265, 2021). "To test if the activation of Akt and Rac1 was involved in hypoxia-induced upregulation of Fascin-1, we used EHop-016 (Rac1 inhibitor) and MK-2206 (Akt inhibitor) to suppress Akt and Rac1 activation in liver cancer cells." (PMID 34897283, 2021). "Our research has some drawbacks, including that RAC1 markers have an independent prognosis in liver cancer." (PMID 35493265, 2021). "In conclusion, we observed the overexpression of Rho protein markers (RhoA and Rac1) in different liver cancer cells when they were stretched for a prolonged period." (PMID 32731493, 2020). "It is shown that that stretching liver cancer cells significantly increases the expression levels of RhoA and Rac1 in HCC and cholangiocarcinoma cell lines." (PMID 32731493, 2020). "In the quest of elucidating the role of mechanical stimulation in the mechanobiology of liver cancer cells, this paper evaluates the effect of stretching on the expression levels of RhoA and Rac1 in different types of liver cancers." (PMID 32731493, 2020). "The results indicated that RAC1 expression was also significantly higher in liver cancer tissues than in adjacent normal tissues." (PMID 31873123, 2019). "Actually, in HGF-stimulated liver cancer cells, we found that Arf6-KD inhibited Rac1 activation and further over-expression of Arf6(Q67L) partially restored such inhibition." (PMID 31752956, 2019). "We detected RAC1 protein expression in 100 pairs of liver cancer tissues through immunohistochemistry." (PMID 31873123, 2019). "Wu found through network pharmacological analysis that the YQJPJD formula mainly regulates potential therapeutic targets of liver cancer through key ingredients such as luteolin, quercetin and baicalin and exerts anti-liver cancer effects through core targets such as RAC1, MAPK3, and RHOA." (PMID 39806972, 2025). "In addition, YAP also promotes multi-drug resistance of liver cancer cells through the RAC1-Ros-MTOR pathway, thereby inhibiting autophagy-related cell death." (PMID 35173685, 2022). "miR-365 and miR-194 modulate liver cancer stem cells via the RAC1 pathway." (PMID 35847360, 2022). "Specifically, we revealed that DOCK1 inhibition by shRNAs or TBOPP, a DOCK1 selective inhibitor, suppressed metformin-induced RAC1 activation, thus enhancing the anti-tumor effects of metformin in both patient-derived organoids and mouse models of liver cancer." (PMID 35217990, 2022). "First, we used TCGA data and GSE76427 to evaluate the prognostic value of RAC1 in liver cancer." (PMID 35493265, 2021).
liver cancer (continued). "Studies show that miR-194 inhibits liver cancer stem cell expansion by regulating RAC1 pathway." (PMID 35082837, 2021). "However, in liver cancer cells MMP8 activates PI3K/Akt/Rac1 signalling pathway leading to increased aggressiveness." (PMID 34059618, 2021). "However, the prognostic performance and clinical landscape of RAC1 in liver cancer are rarely reported." (PMID 35493265, 2021). "Rac1 is found to upregulate in liver cancer patients and predict poor prognosis." (PMID 34897283, 2021). "Many studies have found that the expression of RAC1 is significantly increased in liver cancer." (PMID 35493265, 2021). "MiR-142-3p targeted RAC1 to inhibit the migration and invasion of liver cancer cells." (PMID 35493265, 2021). "Therefore, exploring the expression and prognostic characteristics of RAC1 is critical for new treatments of liver cancer." (PMID 35493265, 2021). "In this study, we investigate whether the mechanical stretching of liver cancer cells can lead to the overexpression of Rho A and Rac1." (PMID 32731493, 2020). "Moreover, whether inhibition of Rac1 can not only prevent the drug resistance of sorafenib in liver cancer, but also affect other drug resistance, such as lenvatinib, is needed to investigate in future studies." (PMID 35847360, 2022). "Therefore, the new RAC1 marker can be used as a potential prognostic biomarker for liver cancer." (PMID 35493265, 2021). "However, whether RAC1 is also involved in the AURKAPS1-induced enhancement of liver cancer progression needs to be further studied." (PMID 31873123, 2019). "In summary, seven of the genes (VEGFA, CTNNB1, SPP1, PPARG, RAC1, HSP90AA1, and LGALS3) were highly unregulated in patients with liver cancer." (PMID 35069936, 2022). "Comparing normal liver tissue samples (225 patients) and liver hepatocellular carcinoma (LIHC) samples (371 patients), the expression of the genes: RhoA, Rac1, LIMK1, LIMK2, ROCK1, ROCK2, MLCK2, and PAK4 is upregulated in liver cancer." (PMID 35241781, 2022). "To further evaluate the influence of Akt/Rac1 axis on hypoxia-induced Fascin-1, we forced expression of PTEN or Myr-Akt1 in liver cancer cells." (PMID 34897283, 2021). "Inhibition of Akt/Rac1 suppressed migration, invasion, EMT, and stemness of liver cancer cells under hypoxia condition." (PMID 34897283, 2021). "In our study, we found that inhibition of Rac1 activity reduced hypoxia-mediated upregulation of Fascin-1 and suppressed migration, invasion, EMT, and stemness of liver cancer cells." (PMID 34897283, 2021). "Taken together, our results indicated that hypoxia-induced activation of Akt/Rac1 signaling increased Fascin-1 expression and regulated migration, invasion, EMT, and stemness of liver cancer cells under hypoxia." (PMID 34897283, 2021). "Next, we evaluated the influence of Akt/Rac1 signaling on migration, invasion, EMT, and stemness of liver cancer cells." (PMID 34897283, 2021). "Further co-expression network analysis showed that CD147 highly expressed in liver cancer tissues correlates with Arf6, ARNO, and Rac1 expressions." (PMID 31752956, 2019). "The Rac1 activation at membrane compartments may induce multiple events, including changes in cell morphology, formation of actin-based lamellipodia, separation from neighboring cells, and finally exhibit a dramatic increase in migration and invasion of liver cancer cells." (PMID 31752956, 2019). "Further checking their mRNA level in different pathological stages showed that CD147, ARNO, and Rac1 expressions were markedly up-regulated, while ACAP3 expression was significantly down-regulated at stage IV of liver cancer." (PMID 31752956, 2019).
liver cancer (continued). "Mechanistically, metformin facilitates the activation of RAC1 by phosphorylating DOCK1, which in turn attenuates the anti-tumor effects of metformin, leading to the observed unresponsiveness in liver cancer." (PMID 35217990, 2022). "Thus, understanding the role of Rac1 and its interplay among cytoskeletal proteins as well as its role in cell-ECM interactions will be crucial in understanding liver cancer cell invasiveness." (PMID 35241781, 2022). "Moreover, hypoxia-induced upregulation of Fascin-1 was regulated by the Akt/Rac1 signaling, and inhibition of Akt/Rac1 signaling by EHop-016 and MK-2206 restrained migration, invasion, EMT, and stemness of liver cancer cells under hypoxia." (PMID 34897283, 2021). "GEPIA bioinformatics analysis showed that CD147, Rac1 and an Arf6-specific GEF ARNO exhibited higher transcription levels in liver cancer tissues than in matched normal liver tissues, whereas, the mRNA level of Arf6 and other Arf6-specific GEFs or GAPs (except ACAP3) tended to be no different." (PMID 31752956, 2019). "Also, we explored RAC1 expression and found that AURKAPS1 overexpression significantly improved RAC1 levels in liver cancer cells." (PMID 31873123, 2019).